RELA (RELA proto-oncogene, NF-kB subunit)
Diseases named in the same sentence as RELA in open-access papers (continued):
Sharing a sentence is not in itself a finding about the gene and the disease.
tumor (continued). "Although NF‐κB upregulates tumor PD‐L1 expression, the level of RELA expression before radiotherapy initiation remains unknown." (PMID 37614219, 2023). "Similarly, immune/inflammation-related TFs, such as NFKB2, STAT1, and RELA, and FOXO3, showed high activity in CXCL10+MEL and TMSB4X+MEL subclusters, which underlies the immunomodulatory phenotype of tumor cells." (PMID 38065972, 2023). "Immunoblot analysis of tumor cell lines isolated from Rb1FL/FLTp53FL/FLRelaFL/FL animals showed lack of RelA expression in all samples analyzed (n = 3), demonstrating that RelA was efficiently deleted in the tumors from these mice." (PMID 36653597, 2023). "RELA expression was significantly different in primary tumor size and extent, regional lymph nodes, and distant metastases, further indicating that RELA gene may affect tumor progression and poor prognosis in NSCLC by overexpression." (PMID 37770919, 2023). "Based on our findings that NEMO but also RelA ablation delayed tumor development, we hypothesized that persistently elevated NF-κB activation might accelerate and aggravate SCLC." (PMID 36653597, 2023). "Additionally, the cCREs in these genes show high signal in the RELA-driven tumor and low signal in the YAP1-driven tumor." (PMID 37739938, 2023). "We next checked whether genes of the tumor progression-related NF-κB signature evidenced in BRAF-PTCs were actually regulated by RelA or RelB in BRAFV600E cell line models." (PMID 37973791, 2023). "Previous work reported that RelA possesses dual functional roles during pancreatic oncogenesis, by promoting tumor suppression through regulation of inflammatory cytokines or facilitating proliferation of transformed tumor cells and tumor progression through bypassing senescence." (PMID 35402225, 2022). "Additionally, previous studies documented that estrogen withdrawal led to the increased transcriptional activity of p65(RelA) and sustained estrogen-independent tumor growth through upregulation of cyclin D1 and BCL-3." (PMID 36045911, 2022). "Transcription factor (TF) activity prediction, using the DoRothEA resource, to identify potential regulons responsible for the signalling and phenotypes associated with HPS in HiFi tumours revealed a strong association with STAT1, STAT2, IFN (IRF1, IRF9) and NFκB (NFKB1, REL, RELA, RELB) TFs." (PMID 35477539, 2022). "The results indicated that PD-L1 is more highly associated with RelB than RelA in PCa tumour tissues, but no clear correlation was found in peritumoral tissues." (PMID 35177112, 2022). "This early work implied that RelA T505 phosphorylation could lead to a tumour suppressing form of NF-κB in some contexts, which again contrasted with the more usual tumour-promoting activity ascribed to this pathway." (PMID 36240065, 2022). "uncovered genes, including TLE4 and IKZF2, that are associated with T-cell exhaustion and effector function via screening of CAR-T cells, and identified genes, including RELA and NPLOC4, that are essential for tumor susceptibility to tumor killing via the reciprocal screening of GSCs." (PMID 35874698, 2022). "However, when cancer cells escape this protective pathway and switch to becoming addicted to ATR/CHK1 activity, to allow them to cope with high levels of DNA replication stress, T505 phosphorylated RelA will contribute towards tumour survival." (PMID 36240065, 2022). "K314 and K315 on RelA can be methylated by SETD7, leading to destabilization of RelA in a ubiquitination-mediated manner, which results in downregulation of tumor-associated genes, such as IL-6, IL-8 and NOS-2." (PMID 35812730, 2022). "However, despite observing higher levels of proliferation and indications of DNA damage in these RelA T505A tumours, we were unable to obtain mechanistic insights into the reasons why we found earlier onset of disease." (PMID 36240065, 2022). "In contrast, genes such as RELA that inhibit the tumor growing were hypermethylated." (PMID 35359376, 2022).
tumor (continued). "Acetylation of RelA/p65, a subunit of nuclear factor-kappa B (NF-κB), by p300 at K218, K221, and K310 activates NF-κB signal pathway and promotes the transcription of interleukin-8 (IL-8) to facilitate angiogenesis and tumor metastasis." (PMID 35216622, 2022). "Representative images of dissected tumours grown as xenografts of control A549 and H1437 cells and their RelA/p65KD derivatives are shown, and statistical analyses of tumour weight differences between control and RelA/p65KD tumour xenografts are provided, respectively." (PMID 34503110, 2021). "From the ginsenoside-target-pathway network, we observed that EGFR, ESR1, ESR2, HSP90AA1, and RELA are all critical genes that we should focus on, which may reveal the anti-tumor mechanism of G-Rk1 and G-Rg5." (PMID 34199025, 2021). "At this time point, NFKB2 and RelA genes were strongly reduced in both healthy and tumor conditions (NFKB2 in h3D vs. 2D p = 0.023; t3D vs. 2D p = 0.014; RelA in h3D vs. 2D p = 0.020; t3D vs. 2D p = 0.006), while the t3D samples also downregulated NFKB1 (p < 0.001)." (PMID 34070750, 2021). "NF-κB RelA/p65 promotes lung epithelial cell tumour growth in vivo by downregulating the metastasis suppressor CD82 and enhancing the epithelial-to-mesenchymal cell transition via integrin-mediated signalling involving the mitogenic ERK, Akt1 and Rac1 proteins." (PMID 34503110, 2021). "Finally, the Myd88L252P tumor gene expression profile not only highlights the canonical NF-κB p65/RelA activation pathway and proliferation, but also strikingly shares an Xbp1 centered lymphoplasmacytic B-cell differentiation signature with MYD88L265P WM." (PMID 34017329, 2021). "Moreover, peripheral anergic T cells, which resemble tumor-infiltrating exhausted T cells, exhibit reduced RelA nuclear translocation." (PMID 33572260, 2021). "We also provide evidence that RelA/p65′s tumour promoting action in NSCLC is due to, at least in part, the downregulation of CD82 that inhibits cell migration and EMT, and the stimulation of ERK and Rac1 through the engagement of integrin-mediated signalling as revealed by bioinformatics analysis." (PMID 34503110, 2021). "All RELA fusion variants tested, except a variant lacking the Rel homology domain, were able to induce tumor formation, albeit with different efficacy." (PMID 33228790, 2020). "In addition, the tumor spheroid invasion assay showed that the invasion area was decreased in RELA-inhibited U87MG cells." (PMID 32127518, 2020). "Recent studies demonstrate that RelA is also involved in tumor angiogenesis in various malignances." (PMID 31952106, 2020). "RelA/p65, which is frequently detected in various cancers as a hallmark of cancer development, is also found constitutively activated in nearly 70% of PDAC tumours and most PDAC cell lines." (PMID 32364285, 2020). "Interestingly, they observed that the expression of RELA (p65) was reduced favoring tumor shrinkage." (PMID 31602271, 2019). "However, L1Cam, a surrogate marker for RELA fusion-gene positivity, was detected only in a subfraction of tumor cells." (PMID 31480400, 2019). "In a comparative study of shRNAs targeting RelA or RelB, OC cells grown in tumor-initiating cell (TIC) culture conditions had significantly fewer Ki67 positive, proliferative cell populations and reduced viability with loss of RelA, compared with the loss of RelB." (PMID 31443240, 2019). "However, deletion of Stat3 in the myeloid compartment also reduces RelA acetylation in tumor cells, signifying the importance of the initial cytokine network to maintain constitutive RelA activity." (PMID 31277415, 2019). "Thus, p68-mediated upregulation of RelA and consequent activation of NF-κB signaling was followed by the elevated expression of NF-κB target genes henceforth accelerating the process of tumor formation and metastasis." (PMID 31351496, 2019). "Our observation suggested the presence of unknown machinery enhancing the protein amount of p65/RelA in tumor samples." (PMID 31580526, 2019).
tumor (continued). "We show that trabectedin modulates RelA/p65 transcriptional activity in senescent tumor cells." (PMID 29731994, 2018). "Interestingly, RelA overexpression promoted tumor growth, whereas RelB overexpression decreased tumor growth." (PMID 29874793, 2018). "Although these signatures were excluded from this study, these may be important because TGFβ and LEF1 signatures are involved in epithelial‐to‐mesenchymal transition (EMT) and NFκB and RELA signatures are involved in tumor immunity." (PMID 29862663, 2018). "The association of tumor size with nuclear localization had significance with RelA (p < 0.05) but not with p50 subunit (p = 0.655)." (PMID 30225173, 2018). "The effect of telomerase on the strong activation of colony formation of tumor stem cells could be repressed by siRNA knockdown of RELA." (PMID 29673141, 2018). "Phosphorylation of RELA/p65 promotes DNMT-1 to represses BRMS1 tumor metastasis." (PMID 29467412, 2018). "PTX3 and RELA were negatively correlated with tumor volume in our cohort." (PMID 28327132, 2017). "However, both NFKB1 and RELA protein expression showed up-regulated in tumor samples compared with paired normal gastric tissues after quantified normalization (P = 0.004 and P = 0.012 respectively)." (PMID 26801246, 2016). "The effect of NFKB1 and RELA expression on in vivo tumor growth was also studied." (PMID 26801246, 2016). "Both NFKB1 and RELA were mainly localized in the cytoplasm of the tumor cells." (PMID 26801246, 2016). "Moreover, RelA T505A mice were more likely to display large (>5 mm diameter) tumours (6/12 for homozygotes, 2/9 for heterozygotes) compared to WT mice, where none were seen at this time point (0/13)." (PMID 26853469, 2016). "We found that nuclear RelA from Stat5 knockdown tumor cells showed increased interaction with IκBα." (PMID 27027438, 2016). "We reasoned by recording both the cytoplasmic and nuclear content of RelA, we might gain a more accurate impression of NF-kB activation in the tumor." (PMID 26460486, 2015). "Importantly, tumor area RelA expression was correlated with the intensity of inflammatory infiltration, whereas RelB expression was identified in proliferating tumor cells." (PMID 26147201, 2015). "Interestingly, tumor RelA expression was correlated with inflammatory infiltration and tumor RelB expression was collocalized with proliferating tumor cell nuclei." (PMID 26147201, 2015). "In specific, RelB was highly expressed in tumor cells, while RelA and P50 in stromal cells." (PMID 26147201, 2015). "In contrast, STAT3 is required to maintain constitutive NF-κB RelA activity in tumor cells." (PMID 26299368, 2015). "Moreover, NF-κB inhibition in lung epithelial cells by cell-specific ablation of IKK2 or p65/RelA or overexpression of IκBαSR significantly reduced tumour development in vivo in a Kras-driven model of lung adenocarcinoma." (PMID 24952939, 2014). "While a role for RelA and YY1 in the repression of Bim in MM is highly novel, it will be interesting to study whether the YY1-RelA complex is frequently formed in other types of cancers to repress Bim and promote tumor cell survival." (PMID 23874387, 2013). "Importantly, we showed that both YY1 and RelA were essential for the colony forming ability of the MM tumor progenitor cells." (PMID 23874387, 2013). "Our results suggest that inhibition of the noncanonical RelB pathway will target cancer cell subtypes within a tumor that may be unresponsive to RelA inhibition and, consequently, may be part of a more effective treatment strategy for mesenchymal glioma." (PMID 23451236, 2013). "Both of RelA/p65 and hTREX84 are highly expressed in more aggressive cancer indicating that RelA/p65 and/or hTREX84 may have a role in tumor progression and metastasis." (PMID 22952718, 2012). "Patients with RelA-positive tumours had a significantly shortened overall survival." (PMID 17622249, 2007).
tumor (continued). "Considering the tumor suppressing function of FOXO3, rs17069665 and rs4946936 might influence RMS risk and prognosis via regulating the expression of FOXO3 by altering the bindings to MYC, CTCF and/or RELA." (PMID 38720807, 2024). "Another member of the NF-κB family, RelA, is mapped to be translocated to 11q13, a site where a number of genes involved in neoplastic development have already been mapped, suggesting a link between chromosomal translocation and the tumour-inducing role of RelA." (PMID 36899924, 2023). "Importantly, NF-κB RelA/p65 was also activated in cells grown as tumour xenografts in vivo, as documented by the expression of the phosphorylated form of RelA/p65, further suggesting that it is required for tumour growth in vivo." (PMID 34503110, 2021). "The up-regulation of RELA, AKT1, TLR1 and RAF1 and the down-regulation of MAPK9 and MAP3K8 were determined by RT-qPCR, indicating that the enhanced anti-tumor function may associate with T cell immune response and proliferation related Toll-like receptor-Akt-NF-κB signaling pathway." (PMID 35046962, 2021). "The changes in the EMT programme and cell migration associated with the loss of RelA/p65, in conjunction with the changes expression of several cell surface genes may be related to the plasticity cell states recently described in human LUAD tumours." (PMID 34503110, 2021). "Indeed, MCP-1 and IL-8 are transcriptional targets of NFKB1 and RELA in tumor cells." (PMID 29928478, 2018). "However, RelA and P50 were predominantly expressed in intratumoral stroma, but RelB in tumor cells." (PMID 26147201, 2015). "This tumor-host interaction could play a role in high level of NF-κB/RelA activity observed in malignant cells because the development of cancer metastases is determined by the interaction of tumor cells with their immediate environment, including tissue- or organ-specific cytokines." (PMID 20716363, 2010). "We determined expression of the NF-κB subunit RelA/p65 in normal pancreas parenchyma, in chronic pancreatitis, in pancreatic intraepithelial neoplasia (PanIN) and in invasive pancreatic carcinoma and correlated the expression patterns to clinicopathological tumour characteristics." (PMID 17622249, 2007). "Single-cell transcriptomic analysis and multiplex staining in primary tumors reveal distinct spatial and cellular distribution patterns, with RELA and RELB active in separate tumor and microenvironmental compartments." (PMID 41844578, 2026). "Enrichment analysis showed that NF‐kB‐related factors (REL, RELA and NFKB1) were enriched in tumour Te‐EVs." (PMID 40326665, 2025). "Among the NF-κB protein family members, including RelA, RelB, c-Rel, p50, and p52, p50 (NFKB1) has been identified as a significant tumor-promoting factor in cancer proliferation and metastasis, correlating with poor patient survival 33,34." (PMID 41041071, 2025). "In conclusion, EBV-induced LINC00944 contributes to OSCC progression by enhancing tumor cell migration, invasion, and macrophage differentiation, potentially regulating these processes through NFKB1 and RELA." (PMID 39941858, 2025).
tumor (continued). "The canonical NF-κB transcription factor RELA is a master regulator of immune and stress responses and is upregulated in pancreatic ductal adenocardinoma (PDAC) tumours." (PMID 39110005, 2024). "Further, expression levels of TF regulators in the NF-κB family (NFKB1, NFKB2, RELA, RELB) were highest in TS3 cluster, reinforcing the notion that NF-κB pathway activation within the tumor epithelium drives TS3." (PMID 39289380, 2024). "PDLIM2 repression in tumor cells thus results in the persistent activation of STAT3 and RelA, leading to MHC-I downregulation and high expression of tumor growth-related genes." (PMID 39718207, 2024). "Studies have shown that inhibition of NF-κB, either by knocking out RelA or IKK2 or by overexpressing a dominant negative form of IκBα, significantly reduces tumor volume, lowers tumor grade, and prolongs survival in mouse models." (PMID 38622735, 2024). "The constitutive NF-κB DNA-binding activity associated with the increased expression of RelA was first demonstrated in PTC- and ATC-derived cell lines, followed by the nuclear localization of RelA in PTC, FTC and ATC tumor tissues." (PMID 37973791, 2023). "In OV90 spheres with miR-452-5p inhibited, sphere formation was significantly decreased in the shNeg control, RELA-silenced, and RELB-silenced cells compared to controls, which is consistent with its role as a tumor-promoting miRNA." (PMID 37175530, 2023). "The combined down-regulation of RELA and MMP9 expression upon SHN3 silencing inhibits tumor growth and cancer invasion, supporting a potential therapeutic value for SHN3 targeting in IL13Rα2-positive tumors." (PMID 37963919, 2023). "This specific SRF signature is shared by tumor subtypes carrying other SRF-fused partner genes, such as the perivascular tumors harboring SRF::RELA fusion." (PMID 36421692, 2022). "Taken together, these mechanistic experiments demonstrate RELA and STAT3 as required for cytokine and tumor microenvironment signaling to PDZK1IP1 induction." (PMID 36253360, 2022). "This distinct subunit-specificity extends our discussion on RELA and/or c-REL being present in solid cancers by showing the subunit-specificity depending on the GBM tumor type." (PMID 36361720, 2022). "A decrease in the levels of RELA, NOD1, CASP8, BCL2L1, ELK1, and IKBKB was identified in the poorly differentiated (G3) tumours compared with the moderately differentiated (G2) ones." (PMID 36433652, 2022). "Our prediction was that a mutation of this site that prevented its phosphorylation would break a link between RelA, CHK1 and DNA replication stress, removing at least some tumour suppressing functions of NF-κB." (PMID 36240065, 2022). "This is in contrast to the tumor suppression by cancer cell–intrinsic PDLIM2, which depends on both STAT3 and RelA." (PMID 33539325, 2021). "In summary, the following marker genes were used for subsequent analysis in supratentorial tumours: RELA, ELL3, FBP2, PCP4L1, and MYO3A for detection of RELA+ tumours; and MRAP, IGF1, CAPS, and WWC1 for detection of YAP1+ tumours." (PMID 34314101, 2021).